PRDM4 (PR/SET domain 4)
Description:
May function as a transcription factor involved in cell differentiation.
Synonyms: PFM1
Tractability: PROTAC: ubiquitination databases record sites on it.
Gene: Protein-coding gene on chromosome 12 (107,732,867 to 107,761,327, reverse strand). Ensembl gene ENSG00000110851.
Subcellular location: Nucleus
Subcellular location (Human Protein Atlas): Nucleoplasm
Pathways (Reactome):
Signal Transduction: p75NTR negatively regulates cell cycle via SC1
Gene Ontology:
Molecular function: protein binding; sequence-specific double-stranded DNA binding; DNA-binding transcription activator activity, RNA polymerase II-specific; DNA-binding transcription factor activity, RNA polymerase II-specific; histone methyltransferase binding; RNA polymerase II cis-regulatory region sequence-specific DNA binding
Biological process: positive regulation of transcription by RNA polymerase II; regulation of gene expression; transcription by RNA polymerase II
Cellular component: nucleoplasm; histone methyltransferase complex; nucleus
Genetic constraint (gnomAD): Loss-of-function variants: 37 observed, 66.28 expected, observed/expected ratio (o/e) 0.56, 90% interval 0.43 to 0.73. The upper end of that interval is the gene's LOEUF score, 0.73, which puts it in group 3 of 6, group 1 being the genes least tolerant of losing a copy. Missense variants: 852 observed, 1,045.4 expected, observed/expected ratio (o/e) 0.82, 90% interval 0.77 to 0.86. Synonymous variants: 339 observed, 366.02 expected, observed/expected ratio (o/e) 0.93, 90% interval 0.85 to 1.01.
Homologues: Orthologues: chimpanzee PRDM4 (99% identical), macaque PRDM4 (99% identical), dog PRDM4 (97% identical), pig PRDM4 (97% identical), rabbit PRDM4 (96% identical), mouse Prdm4 (94% identical), rat Prdm4 (94% identical), guinea pig PRDM4 (91% identical), tropical clawed frog prdm4 (72% identical), zebrafish prdm4 (59% identical). Paralogues in human: ZNF646 (13% identical), ZNF407 (12% identical), ZNF527 (11% identical), ZNF319 (11% identical), ZNF777 (10% identical), ZNF852 (10% identical), WIZ (10% identical), ZKSCAN7 (10% identical), ZNF287 (10% identical), ZNF416 (10% identical), ZNF530 (10% identical), ZBTB17 (10% identical), and 38 more.
Diseases named in the same sentence as PRDM4 in open-access papers:
PRDM4 is named in the same sentence as 18 diseases in open-access papers, as found by Europe PMC text mining. Sharing a sentence is not in itself a finding about the gene and the disease. The quoted sentences say what the papers report.
cervical carcinoma (2 papers, 2021 to 2025). A carcinoma arising from either the exocervical squamous epithelium or the endocervical glandular epithelium. "Here, both immunohistochemistry (IHC) and Western blot assays demonstrated that the expression of PRDM4 in cervical cancer tissues was much lower than that in the normal cervix." (PMID 33846573, 2021). "To explore the molecular function of PRDM4 in cervical cancer cells, we performed a transcriptome sequencing analysis of three HeLa-PRDM4 monoclonal cell lines and HeLa-GFP monoclonal cell lines, and a total of 15,812 genes were detected." (PMID 33846573, 2021). "Here, we found that PRDM4 inhibited cell proliferation and tumor formation in cervical cancer by blocking the cell cycle transition from G0/G1 to S phase by regulating cell cycle checkpoint factors, including p21, p27, Cyclin D1, Cyclin E, and CDK4." (PMID 33846573, 2021). "A xenograft assay showed that PRDM4 overexpression in the cervical cancer cell lines SiHa and HeLa dramatically inhibited cell proliferation and tumorigenic potential in vivo." (PMID 33846573, 2021). "All of these results further confirmed that PRDM4 inhibited the proliferation and tumorigenicity of cervical cancer cells by suppressing the PI3K/AKT signaling pathway via the transactivation of PTEN." (PMID 33846573, 2021). "Conversely, the silencing of PRDM4 promoted cervical cancer cell proliferation and tumorigenic potential." (PMID 33846573, 2021). "All of these results demonstrated that PRDM4 suppressed the tumor growth of cervical cancer in vivo." (PMID 33846573, 2021). "Immunocytochemistry and Western blot assays revealed PRDM4 expression in the cervical cancer cell lines HeLa, SiHa, C33A, and CaSki." (PMID 33846573, 2021). "To investigate the mechanism by which PRDM4 inhibited cervical cancer cells, we obtained cell cycle profiles by FACS analysis." (PMID 33846573, 2021). "For analysis of the function of PRDM4 in cervical cancer cells in vivo, a total of 1 × 106 PRDM4-overexpressing HeLa or SiHa cells, as well as the respective control cells, were injected subcutaneously into female nude mice at the same time to assess the tumor formation potential." (PMID 33846573, 2021). "Additionally, the TCGA database showed that the mRNA level of PRDM4 in cervical cancer tissues was significantly positively related to the PTEN mRNA level, with an R of 0.25 (p < 0.01)." (PMID 33846573, 2021). "At present, we are the first to reveal that PRDM4 could inhibit cell proliferation and tumor formation in cervical cancer by inactivating the PI3K/AKT signaling pathway by transactivating the expression of the suppressor PTEN." (PMID 33846573, 2021). "Moreover, as the PRDM4 expression level increased, the probability of cervical cancer patient survival significantly increased, as shown by the Kaplan–Meier estimator (p = 0.0012)." (PMID 33846573, 2021). "Here, we also found that PRDM4 could inhibit the migration and invasion of cervical cancer cells via the PI3K/AKT pathway." (PMID 33846573, 2021). "Additionally, the Gene Expression Omnibus database showed a much lower PRDM4 mRNA level in 197 cervical cancer tissues than in 68 normal cervical tissues (p < 0.05)." (PMID 33846573, 2021). "To explore the mechanism by which PRDM4 inhibited the tumor formation of cervical cancer in vivo, we evaluated whether PRDM4 overexpression or silencing could influence cell proliferation by cell counting, cell viability, and tumorsphere formation assays in vitro." (PMID 33846573, 2021).
cervical carcinoma (continued). "Additionally, whether the mechanism of PRDM4-mediated PTEN transcriptional regulation in cervical cancer involves the recruitment of a posttranscriptional modification-related protein that plays a negative regulatory role requires more in-depth research." (PMID 33846573, 2021). "All of these results indicated that PRDM4 inhibited cell proliferation and tumor growth, possibly by regulating cell cycle-related genes, including p27, p21, Cyclin D1, and CDK4, in cervical cancer." (PMID 33846573, 2021). "Here, PRDM4 was shown to inhibit cell proliferation and tumorigenesis by decreasing the activity of the PI3K/AKT pathway by transactivating PTEN in cervical cancer." (PMID 33846573, 2021). "Therefore, our data suggest that PRDM4 inhibits cell proliferation and tumorigenesis by downregulating the activity of the PI3K/AKT signaling pathway by directly transactivating PTEN expression in cervical cancer." (PMID 33846573, 2021).
gastric cancer (2 papers, 2020 to 2025). A primary or metastatic malignant neoplasm involving the stomach. "A later study recognized an involvement of PRDM4, which was regulated by hsa-miR-373, in the gastric cancer recurrence with the potential to act as a new prognostic biomarker in predicting recurrence risk for gastric cancer patients." (PMID 32290321, 2020).
Insulin resistance (2 papers, 2018 to 2021). Increased resistance towards insulin, that is, diminished effectiveness of insulin in reducing blood glucose levels. "Additionally, PRDM4, as the target gene of the PI3Kα-AKT1 signaling pathway, has been shown to increase energy expenditure, inhibit weight gain and improve insulin resistance." (PMID 33846573, 2021).
melanoma (2 papers, 2023 to 2024). A malignant, usually aggressive tumor composed of atypical, neoplastic melanocytes. "PRDM4 knockdown increases cell growth, proliferation, migration, invasion, tumor initiation, and progression, emphasizing an opposite role in melanoma." (PMID 37834160, 2023). "EP400, Mi-2β, PRDM4, NCOA6 or CARM1 silencing significantly induced the response to T-cell attack in melanoma cells, and led to more than 20% of the melanoma cells to be eliminated by T-cell-mediated killing." (PMID 38461299, 2024).
prostate carcinoma (2 papers, 2021 to 2025). A carcinoma that arises from epithelial cells of the prostate gland. "However, it has been reported that PRDM4 interacts with the WW domains of YAP to mediate the expression of ITGB2 and other YAP target genes, inducing cell invasion and tumorigenesis in prostate cancer." (PMID 33846573, 2021).
dihydrolipoamide dehydrogenase deficiency (1 paper, 2021). "This locus is associated with dihydrolipoamide dehydrogenase deficiency and is a TF-binding site for PRDM4 (involved in cell differentiation)." (PMID 33917565, 2021).
Obesity (1 paper, 2018). Accumulation of substantial excess body fat. "Adipose-specific expression of Prdm4 enhanced thermogenesis and prevented obesity and metabolic diseases." (PMID 30158592, 2018). "In conclusion, treatment with the small molecule butein and adipose-specific induction of Prdm4 prevented obesity and metabolic diseases in HFD-fed mice." (PMID 30158592, 2018). "Similar anti-obese effects were observed in second transgenic lines (Tg#2), further showing the protective role of adipose Prdm4 in HFD-induced obesity." (PMID 30158592, 2018). "Adipose-specific transgenic expression of Prdm4 recapitulated the butein’s actions in stimulating energy expenditure, cold tolerance, and thermogenic gene expression, resulting in prevention of obesity and improvement of metabolism." (PMID 30158592, 2018). "Having observed selective induction of Prdm4 by butein in adipose tissue, we hypothesized that adipose Prdm4 might play a role in thermogenesis and obesity." (PMID 30158592, 2018).
pancreatic cancers (1 paper, 2011). "PRDM4 (PFM1) is located at a tumor suppressor locus 12q23-q24.1 commonly deleted in ovarian, gastric and pancreatic cancers." (PMID 22087297, 2011).
squamous intraepithelial lesions (1 paper, 2021). "In our clinical specimens, PRDM4 protein expression was detected in normal cervix (NC, N = 38), high-grade squamous intraepithelial lesions (HSILs, N = 30), and invasive cervical squamous cell carcinoma (SCC, N = 60) using immunohistochemistry (IHC)." (PMID 33846573, 2021).
cancer (6 papers, 2013 to 2025). A tumor composed of atypical neoplastic, often pleomorphic cells that invade other tissues. "Additional work will be necessary to explore Prdm4 functional contributions to tissue homeostasis, maintenance of hematopoietic stem cells, lymphocyte differentiation, and its possible roles in cancer." (PMID 23918801, 2013). "Prdm4 was initially cloned as a candidate tumor suppressor gene in human cancers and characterized as a cytoplasmic effector molecule acting downstream of the p75 neurotrophin receptor in response to nerve growth factor signaling." (PMID 23918801, 2013). "Prdm4 inactivates PI3K/AKT signaling (also promoted by TCL1), which inhibits cancer cell proliferation and tumor formation." (PMID 38469292, 2024). "Similarly, for INMON, FOXO3 and IRF5 were common TFs in healthy and early-stage tissues (e.g., BRCA1-mut); specifically, PRDM4 was the TF in precancer stages (e.g., Goiters and HT) while ATF2 and RUNX1 were enriched in cancers (e.g., ESCC and IDC)." (PMID 38645221, 2024). "In the cancer process, most PRDM family proteins, including PRDM4, are catalytically inactive." (PMID 33846573, 2021). "However, the promoter methylation levels of PRDM3, PRDM4, PRDM6, PRDM11, and PRDM12 do not show significant differences across all cancer types." (PMID 39468462, 2024).
tumor (4 papers, 2013 to 2024). "Furthermore, the loss of PRDM4 was associated with poor prognosis in patients with gastric cancer and may act as a tumor suppressor." (PMID 33846573, 2021). "Prdm4 is a transcription regulator located in the tumor suppressor locus involved in cell proliferation and differentiation." (PMID 38469292, 2024). "A previous study showed that PRDM4 maps to a tumor suppressor locus on human chromosome 12q23-q24.1." (PMID 33846573, 2021). "Upregulation of tumor-suppressing genes Prdm4 and Vezt was also observed in these cells." (PMID 38469292, 2024). "In addition, the tumor formation inhibited by PRDM4 overexpression was reversed when PTEN was silenced (p < 0.05)." (PMID 33846573, 2021). "In addition, the IHC score for Ki67 staining was significantly decreased in the tumor tissues formed by the PRDM4-overexpressing cells but dramatically increased in the tumors with stable silencing of PRDM4 compared to the control tumors (p < 0.05)." (PMID 33846573, 2021). "Similarly, compared to the control mice, the mice implanted with the PRDM4-silenced HeLa and SiHa cells (105 cells) showed larger tumor volumes, with a 2.6–3.7-fold increase in tumor size and a 1.7–2.1-fold increase in tumor weight; these mice also had a shortened tumor-free survival (p < 0.05)." (PMID 33846573, 2021). "Additionally, the weights of the tumors derived from the PRDM4-overexpressing HeLa and SiHa cells were much lower than those from the GFP control cells (p < 0.05), and these mice also exhibited longer tumor-free survival (p < 005)." (PMID 33846573, 2021).
PRDM4 also shares sentences with these, for which no sentence is quoted: breast carcinoma (2 papers); hepatocellular carcinoma (1); metabolic disease (1); non-small cell lung carcinoma (1); osteosarcoma (1); ovarian carcinoma (1); uterine corpus endometrial carcinoma (1).